EGFR (epidermal growth factor receptor)
Diseases named in the same sentence as EGFR in open-access papers (continued):
Sharing a sentence is not in itself a finding about the gene and the disease.
endometrioid adenocarcinoma (4 papers, 2010 to 2021). An adenocarcinoma characterized by the presence of malignant glandular epithelial cells resembling endometrial cells. "We comprehensively analyzed EGFR and HER2 expression levels in endometrioid carcinoma, demonstrating that EGFR mRNA and protein were highly expressed in low-grade endometrioid tumor compared to high-grade endometrioid tumor." (PMID 26673416, 2015). "In the present study, we demonstrate that both EGFR mRNA and EGFR protein were highly expressed in low-grade endometrioid carcinoma, but the expression was low in high-grade endometrioid carcinoma." (PMID 26673416, 2015). "In this study, we found that EGFR protein was highly expressed in low grade endometrioid carcinoma tissue and that the proliferation of an EC cell line with high EGFR expression was attenuated by erlotinib, an EGFR tyrosine kinase inhibitor." (PMID 26673416, 2015). "Immunohistochemical analysis and RT-PCR revealed the presence of significant EGFR and EGFR mRNA expression in low-grade endometrioid carcinoma in comparison with high-grade endometrioid carcinoma." (PMID 26673416, 2015).
eosinophilia (4 papers, 2020 to 2023). "This is the reason that the four EGFR-TKIs present statistical significances in SMQ: “drug reaction with eosinophilia and systemic symptoms syndrome”." (PMID 32179761, 2020). "Eosinophilic airway inflammation induced by expressing-IL13 gene was not improved by treating with an EGFR inhibitor alone, but the combination therapy of EGFR inhibitor and dexamethasone suppressed airway eosinophilia and neutrophilic inflammation." (PMID 33217964, 2020).
epithelial dysplasia (4 papers, 2012 to 2020). "Constitutively activated KRAS subsequently upregulates the endogenous expression of the upstream protein epidermal growth factor receptor (EGFR) and induces its hyperactivation, and increased RAS levels and EGFR activity induce robust increases MEK/ERK activity, leading to intraepithelial neoplasia." (PMID 33008426, 2020).
epithelioid sarcoma (4 papers, 2018 to 2025). An aggressive malignant neoplasm of uncertain differentiation, characterized by the presence of epithelioid cells forming nodular patterns. "One patient with epithelioid sarcoma had a pathogenic activating mutation in exon 18 (EGFR p.G719D) and achieved a stable disease per RECIST 1.0 for more than 6 months, with 18% decreased of the target lesions as compared with baseline." (PMID 32337094, 2020). "In EGFR-overexpressing epithelioid sarcoma, EGFR transcript downregulation in VAESBJ and GRU1 corresponded to 66 and 64%, and 59 and 69% after 8 and 24 h, respectively." (PMID 34281526, 2021). "It differentially regulated EGFR, FGFR1 and FGFR2, leading to downregulation of EGFR in epithelioid sarcoma and to mesenchymal-to-epithelial transition whereas in rhabdoid tumor cells, EGFR was strongly upregulated and reinforced the mesenchymal phenotype." (PMID 34281526, 2021). "Similar to epithelioid sarcoma, EGFR overexpression is present in certain epithelial cancers but overexpression alone does not predict treatment response to EGFR inhibition, in contrast to kinase domain mutations, e.g. in exons 18–21 of EGFR in NSCLC patients." (PMID 34281526, 2021). "Intrinsic EGFR overexpression in epithelioid sarcoma maintains the cell’s mesenchymal traits which are in part reversible by panobinostat." (PMID 34281526, 2021). "In epithelioid sarcoma, EGFR overexpression is characteristic and combined inhibition of EGFR and mTOR has been suggested." (PMID 34281526, 2021). "TOR activation was also found in 27 epithelioid sarcoma human samples and 2 cell lines expressing EGFR." (PMID 29492209, 2018). "EGF clearly opposed this effect, relating EGFR signaling to epithelioid sarcoma dedifferentiation." (PMID 34281526, 2021). "This is supported by our results showing erlotinib not reducing proliferation in epithelioid sarcoma cells, and consistent with the absence of EGFR tyrosine kinase mutations in this malignancy." (PMID 34281526, 2021). "In addition to its antiproliferative and cell death-promoting effect, panobinostat differentially regulated expression of EGFR in epithelioid sarcoma and rhabdoid tumor which, according to our knowledge, has been only described in carcinomas so far." (PMID 34281526, 2021). "Functionally, next to the strong cytotoxic effect through induction of apoptotic cell death, HDAC inhibition led to significant EGFR downregulation in epithelioid sarcoma which is one of the best characterized oncogenes, and its activation is tightly related to poor survival and cancer progression." (PMID 34281526, 2021). "In EGFR-overexpressing epithelioid sarcoma, the combination of erlotinib and panobinostat might have further hampered residual oncogenic EGFR-mediated signaling and thereby reduced cell proliferation and -survival, in addition to largely reduced EGFR levels by panobinostat alone." (PMID 34281526, 2021). "We show that differential regulation of EGFR and FGFR2, and partial reversion of EMT in epithelioid sarcoma is induced by HDAC inhibitor panobinostat." (PMID 34281526, 2021). "Despite EGFR overexpression, as confirmed by RT-qPCR, both epithelioid sarcoma cell lines were not sensitive to erlotinib." (PMID 34281526, 2021).
follicular carcinoma (4 papers, 2013 to 2023). "Furthermore, EGFR, Akt pathways are activated in anaplastic and follicular thyroid cancers." (PMID 34131102, 2021).
Hyperinsulinemia (4 papers, 2014 to 2021). An increased concentration of insulin in the blood. "Hyperinsulinemia with increased levels of insulin-like growth factors also promotes tumor growth and causes EGFR-TKI resistance in NSCLC cells." (PMID 34868942, 2021). "First, we examined lamellar tissue from healthy Standardbred horses and those with induced hyperinsulinemia and laminitis for EGFR distribution and quantity using immunostaining and gene expression, respectively." (PMID 31805097, 2019). "Therefore, targeting IGF-1R pathway, reversal of hyperinsulinemia and IGF by dietry recommendations or metformin may decrease resistance of EGFR-TKI as well as reduce the risk of cancer recurrence in tumor patients." (PMID 25048361, 2014). "Metformin and hyperinsulinemia changed the expression of extracellular proteins (e.g. metformin: CTSL, EGFR, IL5, KLK3; insulin: IL4, IL15, PGC, SORL1)." (PMID 33690729, 2021).
Hypoalbuminemia (4 papers, 2020 to 2025). The concentration of albumin in the blood circulation is below the lower limit of normal. "EGFR downregulation in response to dietary protein deprivation and hypoalbuminemia is known to suppress the activation of mitogen-activated protein kinase (MAPK), which regulates ERK1 and ERK2 expression." (PMID 32518615, 2020). "The administration of albumin and a high-casein diet also increased the tissue expression of EGFR, ERK1, ERK2, TGF-β, and collagen and decreased that of MMP-8 relative to the hypoalbuminemia control (P < 0.05)." (PMID 32518615, 2020).
Hypocalcemia (4 papers, 2020 to 2025). An abnormally decreased calcium concentration in the blood. "In addition, EGFR inhibitors may cause hypophosphatemia and hypocalcemia by affecting the Na/Pi (sodium-phosphate) co-transporter channels." (PMID 39026680, 2024).
idiopathic pulmonary arterial hypertension (4 papers, 2011 to 2022). A sporadic form of pulmonary arterial hypertension (PAH) characterized by elevated pulmonary arterial resistance leading to right heart failure. "We therefore quantified S100A4, EGF, and EGFR in patients suffering from chronic thromboembolic pulmonary hypertension (CTEPH) and idiopathic pulmonary arterial hypertension (iPAH)." (PMID 35053115, 2022).
immune deficiency (4 papers, 2008 to 2025). "Interestingly, proteins belonging to signalling pathways not chosen to 'anchor' the analysis (such as IMD (= Immune Deficiency) and JNK (= Jun N-terminal kinase)) are classified within signalling modules defined by the 'anchoring' pathways (TGF1 and TOL2 for IMD, HH2 EGFR and TOR RAS2 for JNK)." (PMID 18489752, 2008).
Infertility (4 papers, 2021 to 2026). "Network pharmacology identified linoleic acid, oleic acid, biotin, and esculentic acid as key contributors to the extract's anti-infertility effects, potentially via interactions with EGFR, HIF1, BCL2, TNF, and AKT1." (PMID 42199843, 2026).
intracranial hypertension (4 papers, 2016 to 2025). A finding characterized by increased cerebrospinal fluid pressure within the skull. "Due to their superior CNS penetration and intracranial tumor control efficacy, third-generation EGFR-TKIs are preferred for patients with LM and intracranial hypertension who harbor suspected EGFR mutations." (PMID 40519289, 2025). "Less GBM patients with EGFR Amp developed symptoms of intracranial hypertension (headache and/or vomiting; 40.0% vs. 90.9%)." (PMID 38595969, 2024). "CSF shunt is a powerful tool against severe headache and uncontrollable intracranial hypertension, and leads to a survival benefit with EGFR-TKI therapy following shunt surgery." (PMID 30629621, 2019). "The early infusion of EGFR-CAR NK-92 cells can quickly control tumor growth and decrease tumor size in the brain, providing potential rapid relief of neurologic symptoms and intracranial hypertension." (PMID 27050072, 2016).
inverted papilloma (4 papers, 2018 to 2025). An endophytic benign papillary epithelial neoplasm that results from the invagination and proliferation of epithelial cells in the underlying stroma. "The risk of malignant degeneration of inverted papilloma into SCC has a very high tendency and both human papillomavirus (HPV) and epidermal growth factor receptor (EGFR) mutations can cause inverted papilloma (IP) transformation to SCC and represent distinct pathways to tumorigenesis." (PMID 40717871, 2025). "Epidermal growth factor receptor (EGFR) mutations, frequently observed in inverted papilloma (IP) and associated with low risk of SCC transformation, could represent a potential target in the prognosis and treatment of this cancer type." (PMID 35059992, 2022).
Li-Fraumeni syndrome (4 papers, 2018 to 2023). "To date, the explanation is unclear, and the possibility that these cancers arise within hereditary cancer syndromes, such as the Li-Fraumeni syndrome, should be considered, particularly in EGFR-mutant tumors." (PMID 38213544, 2023).
metastatic squamous cell carcinoma (4 papers, 2011 to 2023). A squamous cell carcinoma which has spread from its original site of growth to another anatomic site. "Duligotuzumab, a bsAb directed against EGFR and HER3, which is currently in phase Ib for first-line treatment of recurrent/metastatic squamous cell carcinoma of the head and neck, was used as a control." (PMID 28450393, 2017).
mismatch repair deficiency (4 papers, 2017 to 2025).
mouth cancer (4 papers, 2006 to 2026). "A higher proportion of patients with age >40 years (73.5% vs. 26.5%), males (58.8% vs. 41.2%) patients with moderate tumor grade (47.1%), oral cavity tumor (32.4%), and having tumor grade of IV presented with high expression of EGFR." (PMID 33273921, 2020). "Furthermore, a targeted therapy that antagonizes the downstream signaling of the epidermal growth factor receptor (EGFR) has been proved to have synergy with radiotherapy in the treatment of mouth cancer." (PMID 41438577, 2026). "As EGFR expression was positively correlated with its genomic‐copy‐number in TCGA‐HNSC cohort, to further elucidate the plausible mechanism of EGFR driven immune suppression, we have created and analysed an integrated gene expression atlas of 66,809 single cells from 55 oral cavity tumours." (PMID 40621643, 2025).
mucinous tumors (4 papers, 2012 to 2023). "Higher EGFR mutation frequency occurs in non-smokers, women, and non-mucinous tumors." (PMID 22363766, 2012).
oral submucous fibrosis (4 papers, 2015 to 2025). "In addition, areca nut components stimulate epidermal growth factor receptor (EGFR) phosphorylation and interleukin (IL)-1α production and induce reactive oxygen species in oral submucous fibrosis." (PMID 31973037, 2020).
ovarian serous carcinoma (4 papers, 2010 to 2025). "Two studies found EGFR staining to be associated with poorer overall survival in cohorts limited to patients with ovarian serous carcinoma." (PMID 28740577, 2017). "In another cohort of 379 serous ovarian carcinomas amplification and membranous protein over-expression of EGFR were also related to poor overall survival." (PMID 21756326, 2011). "In a subgroup analysis, membranous EGFR expression was observed in 25 out of 80 (31.3%) serous ovarian carcinomas and significantly related to poor overall survival in this cancer subtype (log rank, p < 0.001), which was confirmed in a multivariate analysis (HR 4.6, CI 1.6-13.4, p = 0.004)." (PMID 21756326, 2011).
periodontal disease (4 papers, 2015 to 2025). "Importantly, EGFR inhibitors, AG-1478 and gefitinib attenuated alveolar bone loss and inflammation in a ligature-induced experimental periodontal disease mouse model." (PMID 37083725, 2023). "We also examined the expression of EGF and its receptor EGFR that were profoundly modified during periodontal disease." (PMID 28748038, 2017). "Indeed, in healthy gingiva, using immunohistochemistry, EGFR expression was limited to the gingival epithelium, but during the development of periodontal diseases, a significant increase was only observed in the periodontal ligament." (PMID 28748038, 2017). "EGFR is highly upregulated in periodontal disease and may have a pivotal role in regulating cell migration, proliferation and epithelial wound healing." (PMID 26133673, 2015). "Therefore, the balance between EGF and EGFR could constitute an important mechanism of regulation during the pathogenicity process of periodontal diseases, as observed with enzymes such as cathepsins and matrix metalloproteinases with their natural inhibitor counterparts." (PMID 28748038, 2017).
polyp (4 papers, 2018 to 2022). A usually exophytic mass attached to the underlying tissue by a broad base or a thin stalk. "Due to this background dependency, which is reminiscent of the background sensitivity of EGFR on polyp induction, we further show that the enhanced polyp number on the C57BL/6J background can be eliminated in a double deficiency of EGFR and ERBB3 in the intestinal epithelium." (PMID 34843459, 2021).
pterygium (4 papers, 2021 to 2025). A wedge-shaped fibrovascular lesion arising from the bulbar conjunctiva and extending to the cornea. "The high expression of TMEM43 in pterygium, as in cancer, may act as a critical component in the EGFR signaling network to control cell survival, migration, and invasion." (PMID 34249924, 2021).
pulmonary embolism (4 papers, 2005 to 2026). The obstruction of the pulmonary artery or one of its branches by an embolus, sometimes associated with infarction of the lung. "Combination of a systemic STING agonist, MSA-2, with osimertinib, a third-generation EGFR inhibitor, leads to a decline in advanced pulmonary embolism, perhaps through the action of STING on the tumor microenvironment, in mice." (PMID 38139802, 2023). "mCRC patients who are administered regimens with anti-EGFR mAbs have an approximately 1.5-fold increased risk of experiencing venous or pulmonary embolism compared to those not treated with anti-EGFR mAbs20." (PMID 41049433, 2025). "While there was a trend towards increased post-surgical incidence of pulmonary embolus in patients who expressed the EGFRvIII (17.6%) compared to those who over expressed the EGFR only (7.1%) or failed to express EGFR (8.7%), it was not statistically significant (p = 0.36)." (PMID 16236164, 2005).
reovirus infection (4 papers, 2014 to 2024). "Some studies have reported that two mouse cell lines (NR6 and B82), expressing no epidermal growth factor receptors (EGFR), were relatively resistant to reovirus infection, but the same cell lines transfected with the gene encoding EGFR express significantly higher susceptibility." (PMID 38256250, 2024). "The mechanism of oncolysis by reovirus remained largely unknown until murine cell lines transfected with genes encoding the epidermal growth factor receptor (EGFR) demonstrated increased susceptibility to reovirus infection." (PMID 25019061, 2014). "Previous studies reported that two mouse cell lines (NR6 and B82), expressing no EGFR, were relatively resistant to reovirus infection, but the same cell lines transfected with the gene encoding EGFR express significantly higher susceptibility." (PMID 39772250, 2024). "Not surprisingly, subsequent studies investigated the facilitation of reovirus infection by activated downstream EGFR-mediated pathways and, in particular, the activated Ras signaling pathway to uncover potential relationships to the mechanism of selective oncolysis." (PMID 25019061, 2014). "Our observations are in agreement with recent investigations, which have also shown that the vulnerability of malignant cells to reovirus infection may not be dependent upon RAS mutation or an activated RAS pathway (e.g. constitutive EGFR activation)." (PMID 26513296, 2015).
rhabdoid tumor (4 papers, 2015 to 2022). An aggressive malignant embryonal neoplasm usually occurring during childhood. "In rhabdoid tumors, previous reports have associated both cranial and extracranial tumors to elevated EGFR expression, activation and successful pharmacological inhibition, and more recently, in a INI1-dependent context." (PMID 34281526, 2021). "With our results we provide evidence that EGFR serves rather as a differentiation- than a tumor growth factor and, that the discordant EGFR regulation in epithelioid versus rhabdoid tumor cell lines by panobinostat is mechanistically exploited differently." (PMID 34281526, 2021). "In rhabdoid tumor cell line A204, the induced EGFR upregulation serves to resist the differentiating potential of HDAC inhibitors." (PMID 34281526, 2021). "In contrast in the rhabdoid tumor, results point at employment of increased EGFR expression as resistance mechanism." (PMID 34281526, 2021).